MTOR (mechanistic target of rapamycin kinase)
Diseases named in the same sentence as MTOR in open-access papers (continued):
Sharing a sentence is not in itself a finding about the gene and the disease.
breast cancer (continued). "Those are strongly associated with the AKT/PI3P signal transduction circuitry and frequently overexpressed (mTOR) or inactivated (PTEN) in a variety of cancer, including breast cancer." (PMID 31191821, 2019). "In summary, we show that GHR is overexpressed in ER−ve breast cancer cells and inhibiting GHR signaling reduces the activity of the JAK/STAT and AKT/mTOR pathways and inhibits EMT, growth, and metastatic behavior of ER−ve breast cancers." (PMID 30617282, 2019). "It induces autophagy to mediate apoptosis through suppressing Akt/mTOR signaling pathway in human breast cancer MCF-7 and MDA-MB-231 cells, and stimulates AMPK-mTOR-dependent autophagy to induce cell death in apoptosis-resistant cells." (PMID 31719837, 2019). "Pre-clinical studies using cell and mouse models demonstrated the efficacy of dual PI3K/mTOR inhibitors such as BEZ235 or dactolisib (NVP-BEZ235, Novartis) in several types of cancers including breast cancer, lung adenocarcinomas, glioblastoma." (PMID 31817676, 2019). "To further prove the role of PI3K-AKT-mTOR pathway in breast cancer growth and metastasis, we use rapamycin, an inhibitor of mTOR protein, to suppress the PI3K-AKT-mTOR pathway." (PMID 31007610, 2019). "Everolimus, the inhibitor of the mammalian target of rapamycin (mTOR), has been shown to inhibit tumor cell growth through suppression of phosphoinositide 3-kinase (PI3K)/AKT pathway in breast cancer." (PMID 31238539, 2019). "In the current study, XAN, BER, ANG, PSO, IMP were selected on the basis of their best docking scores against breast cancer which was further validated by specific in-vitro assays of ERα, EGFR and mTOR." (PMID 31673107, 2019). "mTOR is targeted by everolimus (along other small molecules; approved by FDA in breast cancer treatment) and is also one of the few intracellular proteins targeted by FDA-approved small molecule drugs (along with CDK4/CDK6 and PARP enzyme)." (PMID 31681603, 2019). "In this study, we found that CLE-10 inhibited the proliferation of breast cancer cells (MDA-MB-231) by inducing apoptosis and pro-death autophagy through the PI3K/Akt/mTOR signaling pathway." (PMID 30897708, 2019). "Dual inhibitors of PI3K and mTOR, BEZ235 and PF-04691502, both demonstrated antitumor efficacy in breast cancer cells and xenograft models, but were also inclined to cause serious side effects in clinical practices." (PMID 30754640, 2019). "AKT can activate autophagy-dependent classical mTOR pathway and inhibition of AKT/mTOR pathway can induce autophagy and help block breast cancer progression." (PMID 30713576, 2019). "In a similar study, the combined use of trastuzumab and rapamycin, a mammalian target of rapamycin (mTOR) inhibitor, was examined in inducing regression of HER2-positive mouse mammary tumors in vivo." (PMID 31598114, 2019). "Approximately 90% of the primary breast cancers overexpressed HER3, p-mTOR, p-4EBP1, p-JAK2, p-STAT3, and 50% overexpressed p-Paxillin." (PMID 31667338, 2019). "Metformin has been studied extensively as a potential therapy targeting KLF5 in other cancer types, such as endometrial, prostate and breast cancer, and some metformin cancer studies have sought to target other gene pathways such as the PI3K/Akt/mTOR pathway." (PMID 31401336, 2019). "In breast cancer, the PTEN/mTOR/STAT3 pathway plays a crucial role in cancer stem-like cell viability and stem maintenance." (PMID 31781676, 2019). "An elevation in endocannabinoids receptor (CB1-R) expression following quercetin treatment has been noted in colon and breast cancer cell lines, which in turn inhibited survival signaling pathways such as PI3K/Akt/mTOR." (PMID 31064104, 2019). "GHR silencing drastically reduced the chemoresistant and metastatic behavior of ER-ve breast cancer cells and also inhibited AKT/mTOR pathway." (PMID 30617282, 2019).
breast cancer (continued). "A study using human breast cancer cell lines and mouse tumor xenografts has shown that activating mutations of PIK3CA and/or decreased expression of PTEN could be responsible of resistance to lapatinib and that this resistance is reversible by double blockade of PI3KCA and mTOR." (PMID 31164152, 2019). "Taking together the results derived from the comparison of the IgG profile of breast carcinomas and control samples, it was found that those mostly related to the AKT/PI3K/mTOR pathway together with PTEN, complemented with c-Kit and Aurora A-signaling." (PMID 31191821, 2019). "Therefore, PI3K/AKT/mTOR signaling pathway is considered as an attractive target for the development of new anticancer agents that could be used alone or in combination with other targeted therapies for treating breast cancer patients." (PMID 29523109, 2018). "To investigate the mechanisms by which AM extract inhibit cell growth and promoted apoptosis in breast cancer cells, we analyzed PI3K/Akt/mTOR signaling pathways after treatment with the AM extract." (PMID 29523109, 2018). "We further demonstrated that the mechanism of inhibition of breast cancer cell growth and invasion by SALL1-NuRD depends on the p38 MAPK, ERK1/2, and mTOR signaling pathways." (PMID 29625565, 2018). "As part of inhibitory effect on breast cancer cells proliferation, the AM extract decreased the expression of p-PI3K, p-GS3Kβ, p-AKT and p-mTOR, and led to breast cancer cell apoptosis." (PMID 29523109, 2018). "Our results demonstrated that AM extract showed a cytotoxic effect on breast cancer cells, and its mechanism of anticancer action seemed to induce breast cancer cell apoptosis via PI3K/AKT/mTOR signaling pathway." (PMID 29523109, 2018). "While functional studies are needed, published reports support the notion that miRNAs differentially expressed in mammary tumors of LP daughters target the tumor suppressive and energy-sensing AMPK pathway resulting in sustained mTOR activity and cell growth." (PMID 30165877, 2018). "In light of the key role of PI3K/Akt/mTOR signaling pathway in governing apoptosis, our study showed that inhibition of PI3K/Akt/mTOR pathway by the AM extract increase the apoptosis of breast cancer cells." (PMID 29523109, 2018). "Currently, targets such as mTOR, PI3K, IGF-1R, Akt, HSP90, and VEGF exhibited significant clinical interests in HER2-positive breast cancer." (PMID 30134903, 2018). "Moreover, some investigators suggest that breast cancer occurs mainly through two mechanisms: one is the amplification of HER2 or overexpression of the receptor tyrosine kinase (RTK) activation pathway; the second is that PI3K/AKT/mTOR pathway proteins undergo specific mutations." (PMID 29614812, 2018). "Treatment of ER-positive breast cancer cells with α-methyl-dl-tryptophan (α-MT), a selective blocker of SLC6A14, leads to amino acid deprivation, inhibition of the mTOR pathway, activation of autophagy, and induction of cancer cell apoptosis." (PMID 29562706, 2018). "A reduction in the dietary protein intake was reported to be effective for inhibiting tumor growth in prostate and breast cancer, possibly through the inhibition of the IGF/Akt/ mTOR pathway." (PMID 29844867, 2018). "Metformin has previously been shown to inhibit the growth of breast cancer cell lines in vitro via AMPK induction and mTOR inhibition." (PMID 30409193, 2018).
breast cancer (continued). "Of note, in human breast cancer cells, a rapid estrogen action involving ERα-mediated activation of the c-Src/PI3K/AKT/mTOR pathway was accountable for the up-regulation of HIF-1α protein expression." (PMID 29996493, 2018). "Twenty-one of the well established breast cancer biomarkers, including CDK4 and MTOR were unaffected by fat tissue in our sequencing data." (PMID 30190792, 2018). "Four of these five patients—two with cervical cancer, one with breast cancer, and one with germline cancer—had at least two molecular alterations involving the PI3K/AKT/mTOR pathway, including STK11 and INPP4B." (PMID 32914004, 2018). "Under standard culture conditions endogenous TFEB was localized to the cytoplasm in the breast cancer cell line MCF7, but was relocated to the nucleus on addition of the mTOR inhibitor Torin 1, indicating that in these cells mTOR controls TFEB localization." (PMID 29992949, 2018). "In breast cancer MDA-MB-453 cells, the treatment with either the mTOR inhibitor, everolimus (10 nM) or the Akt inhibitor, AZD5363 (1 μM) significantly up-regulated KCa1.1 transcription." (PMID 29713287, 2018). "The combined suppression of the CDK4/6 and PI3K/AKT/mTOR pathway already proved to be synergistic in cells derived from T-ALL, malignant pleural mesothelioma, and breast cancer." (PMID 30544932, 2018). "To explore the mechanism of delphinidin-induced autophagy, we examined the expression of the proteins in mTOR signalling pathway, including AKT, mTOR, eIF4e, and p70s6K, in HER-2 positive breast cancer cells." (PMID 29587684, 2018). "To investigate the effect of AM extract on PI3K/AKT signaling pathway in breast cancer cells, we performed western blot analysis of phosphorylated and total- PI3K, GS3Kβ, Akt and mTOR." (PMID 29523109, 2018). "Some of the new drugs such as everolimus (mTOR inhibitor), BYL719, GDC-0941, GDC-0980, and BKM120 (PI3k inhibitors) are being evaluated in combination with fulvestrant for the treatment of breast cancer metastasis." (PMID 29787591, 2018). "Breast cancer is the most prevalent cancer among women, and AXL and MET are the key genes in the PI3K/AKT/mTOR pathway as critical elements in proliferation and invasion of cancer cells." (PMID 30386383, 2018). "This bivalent interaction allows the inhibition of the mTOR complexes and their rapamycin- and AZD8055-resistant forms in breast cancer cell lines." (PMID 29772672, 2018). "YAP is activated by PI3K in hepatocellular and mammary carcinoma, but has been shown to regulate PI3K/AKT/mTOR signaling in the MCF 10A human immortalized mammary epithelial cell line." (PMID 30356686, 2018). "However, upregulated PI3K-Akt-mTOR signaling is clearly associated with chemoresistance, which has been shown in various preclinical cancer models, and chemotherapy response can be augmented in this setting by simultaneous PI3K or Akt inhibition, in particular in ER positive breast cancer." (PMID 28476032, 2017). "In breast cancer, PI3K/AKT/mTOR signalling pathway is generally activated 33, and pathway activation promotes tumour growth and progression." (PMID 28272775, 2017). "In contrast, the intrinsic induction of PD-L1 on the surface of tumor cells is mediated by constitutive oncogenic and transcriptional pathways, such as the PI3K and mTOR pathways in non-small cell lung cancer and the EGFR-MAP kinase pathway in breast cancer." (PMID 28938605, 2017). "Several inhibitors of PI3K and mTOR are in clinical trials for estrogen receptor α-positive (ER+) and HER2-overexpressing (HER2+) breast cancers." (PMID 28423521, 2017).
breast cancer (continued). "The signaling pathways affected by these miRNAs were MAPK, mTOR, Wnt, and TGF-β, and these findings provided a global view about the function of differential expression miRNAs related to drug resistance in breast cancer." (PMID 28574440, 2017). "This third-generation mTOR inhibitor, named RapaLink-1, maintained activity in both rapamycin-resistant and AZD8055-resistant xenografts in breast cancer." (PMID 28822012, 2017). "Similar findings were also reported in acute myeloid leukaemia and in breast cancer stem cells, where it was shown that the PI3K/AKT/mTOR pathway was critical for cancer stem cell proliferation and survival." (PMID 28915623, 2017). "Taken together, our results demonstrate that BME treatment inhibits breast tumor growth, and this anti-tumor activity in breast cancer is, in part, mediated by induction of autophagy and modulation of the AMPK/mTOR pathway." (PMID 29029506, 2017). "Therapy resistance is a major problem in metastatic breast cancer and markers of importance for endocrine resistance (Akt2, FOXO, mTOR, Myc, PI3KCA, and PTEN) were investigated in patients with HR+ breast cancer." (PMID 28489591, 2017). "Given the main difference of oestrogen receptor α (ERα) between two types of breast cancer cells, It is possibly suggested that CPT inhibits mTOR pathway dependent on ERα in breast cancer." (PMID 28272775, 2017). "The PI3K/Akt/mTOR pathway modulates responses to signals communicated through the ER and HER family of receptors in breast cancer, and this pathway is critical in the clinical sensitivity of breast tumor to endocrine therapy." (PMID 29070044, 2017). "Here, we determined the effect of the PI3K/mTOR dual inhibitor BEZ235 and the histone deacetylase inhibitor Trichostatin A (TSA) on human breast cancer." (PMID 28060760, 2017). "In some breast cancers, the PI3K/Akt/mTOR pathway is overactive irrelevant to HER2 and ER/PR status." (PMID 28060760, 2017). "On the other hand, melatonin was shown to inhibit AKT/mTOR signaling in models of ovarian cancer, breast cancer, hepatoma, and melanoma, where AKT/mTOR are aberrantly hyperactivated and contribute to carcinogenesis." (PMID 28878191, 2017). "Prospective trials evaluating PI3K/mTOR inhibitors are warranted, especially in Asian patients with HER2+, HR– advanced breast cancer." (PMID 28399902, 2017). "In summary, we have demonstrated that BME induces autophagic cell death in breast cancer cells, both in vitro and in vivo, through the LC3B/AMPK/mTOR signaling pathways." (PMID 29029506, 2017). "In particular, metformin blocked mTOR-dependent translation, which is essential for the regulation of cell growth, survival, and angiogenesis, in MCF-7 breast cancer cells." (PMID 28193239, 2017). "Anti-tumor activity improved with the addition of a brain-penetrant PI3K/mTOR inhibitor, suggesting that combining targeted therapies is a more effective strategy for treating HER2-positive breast cancer brain metastases." (PMID 28493046, 2017). "Overexpression of HER2 has been shown to increase FASN translation, which alters the activity of the mTOR and the PI3K/AKT signaling pathway in breast cancer cells." (PMID 29112149, 2017). "In summary, GAS5, regulated by mTOR pathway, serves as a ceRNA of miR-21 to regulate PTEN in the development of breast cancer trastuzumab resistance." (PMID 27034004, 2016). "In breast cancer, constitutive activation of PI3K/Akt/mTOR and MAPK/ERK signal pathways is an important event, which regulates multiple cellular processes to promote cancer cell growth, survival, and metastasis." (PMID 26565813, 2016). "Compared to other mTOR inhibitors, such as rapamycin and PP242, metformin treatment exerted more inhibitory effect on proliferation and migration of breast cancer cells." (PMID 27748082, 2016).
breast cancer (continued). "To confirm that PKM2 expression activates mTOR signaling and inhibits autophagy, we analyzed markers of each molecular events in renal cell carcinoma (RCC) and breast cancer samples." (PMID 26876154, 2016). "We also found that protein restriction, independently of caloric intake, strongly inhibits tumor growth in human xenograft prostate and breast cancer animal models, by lowering serum IGF‐1 and reducing mTOR phosphorylation." (PMID 26443692, 2016). "The mTOR inhibitors and mTOR knockdown reduced the protein and mRNA levels of KPNA2 in NSCLC and breast cancer cells." (PMID 27009856, 2016). "The results showed that RQC reduces mTOR pathway activation and induces apoptosis via inhibition of Akt and activation of AMPK in breast cancer." (PMID 27999314, 2016). "MCF7, a breast cancer cell that has constitutive PI3K activation and higher mTOR activity so that it is sensitive to mTOR inhibitor, showed very sensitive response to resveratrol treatment." (PMID 26902888, 2016). "In our study, the corresponding canonical cancer pathways in the HBL tumor transcriptome are GBM, Her-2 breast cancer, EGF and ERBB signaling (EGFR), Wnt-β-catenin signaling (Wnt), STAT3 and JAK/STAT signaling (JAK/STAT), and mTOR signaling pathways (mTOR)." (PMID 27910913, 2016). "In breast cancer, THC inhibits cell proliferation by blocking the cell cycle and inducing apoptotic cell death, while CBD inhibits AKT and mTOR signaling inducing autophagic-cell death." (PMID 27769052, 2016). "In this study, we found simvastatin to induce apoptosis, inhibit proliferation of breast cancer and deactivate sequential cascades of both PI3K/Akt/mTOR and MAPK/ERK pathways." (PMID 26565813, 2016). "In agreement, we demonstrate that CCL5 treatment increases glucose uptake by breast cancer cells, mediated by CCR5 and mTOR-dependent." (PMID 27335323, 2016). "We demonstrate CCL5-inducible rapid activation of the mTOR/AKT pathway as well as phosphorylation of a downstream substrate, GSK3β, in breast cancer cells." (PMID 27335323, 2016). "We also examined an Akt-signaling pathway in SCLC cells since the PI3K/AKT/mTOR pathway is frequently activated in SCLC tumors and exogenous introduction of FOXM1 activates the AKT pathway in breast cancer cells." (PMID 26871945, 2016). "Understanding the proteolytic mechanism responsible for mTOR level in breast cancer may pave the way for improving the efficacy of breast cancer treatment regimens and mitigating drug resistance as well as providing a basis for potential novel therapeutic modalities for breast cancer." (PMID 27748082, 2016). "Collectively, these data warrant testing of SERDs with chromatin modifying agents and inhibitors of mTOR and CDK4 pathways in ER mutant breast cancer models." (PMID 27472462, 2016). "Coincident ERK activation is reported in HER2-positive breast cancer cell lines after MLN0128 treatment and better xenograft tumor regression is accomplished by dual mTOR and HER2 blockade." (PMID 26536665, 2016). "Although the activity of the mTOR inhibitor everolimus has been reported in patients with luminal and HER2+ breast cancers, results of clinical trials with mTOR-specific inhibitors in TNBC have not been published yet." (PMID 27374081, 2016). "Inhibitory effects on mTOR activity by different concentrations of oleocanthal were clearly observed, which led to antiproliferative effects in MCF-7, T47D and MDA-MB-231 breast cancer cell lines, with the latter cells being the most affected." (PMID 26840281, 2016). "Herein, we established target profile of a novel mTOR kinase inhibitor (mTOR-KI) MTI-31 and employed it to study new therapeutic mechanism in breast cancer." (PMID 27563814, 2016). "The differences in response to rapamycin between normal MECs and breast cancer cell lines could be due to differences in insulin-like growth factor receptors (IGFRs), which are expressed at higher levels in cancer cells and mediate feedback to Akt upon mTOR inhibition." (PMID 26132202, 2015).